CD4 (CD4 molecule)
Diseases named in the same sentence as CD4 in open-access papers (continued):
Sharing a sentence is not in itself a finding about the gene and the disease.
infection (continued). "It is particularly striking that, in a virus-infected host, CD4+ memory T cells express their effector functions within hours of infection, but fail to divide for several days." (PMID 18404208, 2008). "CD4+ T cell numbers in the lungs were then recorded during the first 2–12 days of the first and second infection." (PMID 18389078, 2008). "In peripheral blood of experimentally infected macaques, MV infection of both CD4+ and CD8+ T-lymphocytes was observed." (PMID 18421379, 2008). "We found that the frequency of CD4+ T-cells within livers of co-infected individuals was reduced compared to HCV mono-infection." (PMID 18941622, 2008). "CD8 T cells are important for efficient clearance of MNV infection in both the MLN and distal ileum, and they function later in infection than CD4 T cells, being most important at days six and seven." (PMID 19079577, 2008). "In sum, the highly conserved MPR of gp41, which contains continuous epitopes recognized by broadly neutralizing antibodies 2F5, 4E10 and Z13, appears to be essential for both CD4-dependent target cell infection and CD4-independent mucosal entry of HIV-1." (PMID 18925934, 2008). "In summary, this is the first report to show that clearance of H pylori is correlated with an antigen-specific CD4+ T cell response, suggesting immunity against this infection in humans." (PMID 18417532, 2008). "In their central experiment, HIV bound at 4°C prior to co-culture was entirely inhibited by a soluble CD4 (sCD4) protein, and when the DCs were shifted to 37°C before sCD4 addition, the inhibitor still blocked infection." (PMID 18725936, 2008). "Before infection, a dose-dependent decrease in the percentages of CD4+CD25+ cells among CD4+ T cells was observed in offspring of dams exposed to BPA." (PMID 18414636, 2008). "After inoculation with HIV strains YU2 or NL4-3, the mice developed sustained high levels of viremia, and displayed CD4 depletion that was more extensive after infection with NL4-3 than with YU2." (PMID 18237418, 2008). "In the absence of C16, the recruitment of inflammatory cells in the lung and bronchoalveolar lavage was increased early after infection (day 3) and more CD4+ and CD8+ T cells expressed the CD69 activation marker." (PMID 18796705, 2008). "It is interesting to note that while HIV-1 specific memory CD4+ T cells are selectively infected during an ongoing infection as compared with CMV specific memory CD4+ T cells, only a fraction of the HIV-1 specific memory cells are infected." (PMID 18941536, 2008). "Protection generated by Plasmodium infections against blood-stage infection is mediated by helper and effector functions of CD4+ T cells." (PMID 18495039, 2008). "To address this question we compared virus-specific CD4+ T cell responses in WT and IL-6−/− mice approximately three months after infection with influenza virus." (PMID 18389078, 2008). "Together, these findings argued in favor of the Trojan horse model, in which HIV-1 virions tap into an endocytic-exocytic process of DCs to mediate trans-infection of CD4 T cells." (PMID 18584030, 2008). "Seeking to better understand the events involved in HIV-1 trans-infection, we tested the effects of soluble CD4 (sCD4)." (PMID 18584030, 2008). "CD4+ cells accumulate in the inflamed sites as the infection progresses in both the wild-type and knockout mice." (PMID 18320044, 2008). "Clinical data was available from all individuals at 62 days post infection and we compared viral load and CD4+ dynamics up to 15 months post infection in the nine individuals infected with T242N/A146X mutants to those of the rest of the cohort." (PMID 18369479, 2008). "Consistent with our findings, blocking CCR5 antibodies reduced transcytosis of R5-specific HIV-1 through primary genital epithelial cells, resulting in attenuated infection of CD4+ cells." (PMID 18371227, 2008).
infection (continued). "Specifically, CD4+ T cell responses are critical for containment of infection in the mouse TB model and individuals with HIV infection in whom CD4+ T cells are depleted are susceptible to TB." (PMID 18923705, 2008). "Two weeks post-infection, 31.5% of CD4+ T cells produced IFN-γ in PpSP15-mice compared to 7.1% in PpSP44-mice." (PMID 18414648, 2008). "In order to further understand the direct effects of HIV-1 on CD4+ T cells and other cell types, several models of in vitro infection with different HIV-1 strains have been developed." (PMID 18617991, 2008). "NP-2/CD4/FPRL1 cells were highly susceptible to two HIV-2 strains CBL23 and ROD/B: about 60% of cells became HIV-2 antigen-positive on day 6 after infection." (PMID 18577234, 2008). "We found evidence of infection of resting Tregs (HLADR−CD69−CD25hiFoxP3+CD4+ T cells) purified from patients on prolonged HAART." (PMID 18827929, 2008). "In both infections, from day 5 onwards, the vast majority of the IL-10+ cells were CD4+ lymphocytes." (PMID 18401464, 2008). "Cd59a–/– and WT mice were infected with influenza virus, and CD4+ T cells purified from spleens at day8, 12 and42 after infection." (PMID 17429844, 2007). "Experimental infection of CD4+ T cells with HTLV-I and HTLV-II has also been associated with defects in TCR/CD3 expression and function." (PMID 17822534, 2007). "We analyzed immune responses at this early phase of the infection focusing on CD4+ and CD8+ T cells and NK cells." (PMID 17326843, 2007). "Since CD4+ T cells are important for the development of protective immunity and contribute to pathology during blood stage infection, it is important to know if pre-erythocytic stage infections affect this response." (PMID 17555592, 2007). "The infection of OM10.1 represents an artificial situation that allowed the study of CD4 levels in response to infection." (PMID 17663774, 2007). "Equivalent analyses performed 70 days post-infection revealed that only BCGin and BCGin/DNA groups presented significant expression of CD44loCD62Lhi on CD4+ cells compared with infected group." (PMID 17714584, 2007). "Possibly, CRF01_AE cannot replicate to its full extent after early infection due to decreasing levels of available CD4+ T cells." (PMID 17716368, 2007). "Blood parasitaemia and cytokine production was measured in splenic CD4+ T cells at early and later stages of a primary blood stage infection." (PMID 17555592, 2007). "Thirty days after infection, we observed that all immunized mice presented significant percentage of CD4+ cells expressing CD44loCD62Lhi molecules in relation to infected mice." (PMID 17714584, 2007). "In contrast, only BCGin/DNA group presented a significant influx of CD4+ cells after 70 days of infection." (PMID 17714584, 2007). "Direct productive infection of intraepithelial CD4+ T cells occurred very efficiently, reminiscent of the extraordinary HIV-1 susceptibility of CD4+ CCR5+ memory T cells inhabiting the gut mucosae." (PMID 17306567, 2007). "After infection, activated macrophages produce interleukin (IL)-12, which in turn stimulates CD4 T cells to produce Th1 cytokines (IFN-γ and TNF-α), thus linking the innate and adaptive immune responses." (PMID 17655752, 2007). "First, we prepared Treg cells by infection of CD4+CD25+ T cells with recombinant retrovirus carrying the pMXs-IR-Foxp3 vector." (PMID 17284325, 2007). "During continued tenofovir treatment, there was a gradual increase of CD4+ T lymphocyte values to normal pre-infection levels (percentage of CD4+ T lymphocytes: 30–39%; CD4+/CD8+ T-cell ratio 1.25–1.75; absolute CD4+ T lymphocyte counts: ≥ 700 per μl)." (PMID 17417971, 2007). "Changes in CD4 counts between helminth co-infected individuals who cleared their infection following treatment and those who were infected with helminths at the follow-up visit were compared in two studies." (PMID 18160978, 2007).
infection (continued). "Conversely, late isolates were often more CD4-dependent in that productive infection in NP-2/CCR5 cells was in most cases weak and was revealed only after cocultivation of infected NP-2/CCR5 cells with peripheral blood mononuclear cells (CD4-independent-LOW)." (PMID 17645788, 2007). "In comparison, infection of NP-2 cells expressing both CD4 and CCR5 resulted in more efficient syncytia induction and productive infection." (PMID 17645788, 2007). "This chemokine is involved in promoting the recruitment of monocytes to infection sites and has also been proposed to play a role in CD4 T cell Th1/Th2 polarization 29 by negatively regulating the Th1 response." (PMID 17393387, 2007). "This significant increase in absolute CD4+ T cell counts was transient, as values returned to pre-therapy baseline values after 12 weeks of tenofovir therapy (32 weeks of infection; two-tailed paired t test p values ≥ 0.05)." (PMID 17417971, 2007). "Early in infection, Nef removes CD4 molecules that are already present at the cell surface by enhancing their endocytosis and subsequent degradation in lysosomes." (PMID 17937819, 2007). "In vitro latently infected resting CD4+ T cells obtained with the experimental protocol of infection were tested by ELISpot to enumerate replication-competent infected cells before and after polyclonal activation." (PMID 17727722, 2007). "The results show that early in infection CD4-independent-HIGH and neutralization sensitive populations were in majority, since reisolates from all four LTNP and five out of nine SP/P macaques showed this phenotype." (PMID 17645788, 2007). "Maturation of the DCs results in migration to the lymph nodes where HIV-1 can be presented to a pool of CD4+ T-lymphocytes and establish infection." (PMID 17263871, 2007). "At three or four months after infection CD4-independent-HIGH viruses were still isolated in two out of four LTNP animals, while only three out of nine macaques from the P and SP group harbored viruses with the CD4-independent-HIGH phenotype." (PMID 17645788, 2007). "CD4+CD25+ cell numbers expand dramatically during infection, with parallel growth of both CD25+Foxp3+ and CD25+Foxp3– subsets." (PMID 17563918, 2007). "All data available on the preintegration state result from molecular studies in untreated patients or from in vitro infection model of resting CD4+ T cells." (PMID 17727722, 2007). "Four days after infection, animals were sacrificed, and the spleens, which harbor high levels of CD4 T-lymphocytes, were removed." (PMID 17655755, 2007). "In our model, the differences in the rate constants for multiple infections follow naturally from our description of CD4 down-modulation (Equation 3)." (PMID 17967052, 2007). "CD4+ T-cells are fundamental to the development of specific immune responses to infection, particularly intracellular pathogens." (PMID 17502001, 2007). "Here, we follow Dixit and Perelson and assume that the infection rate k is directly proportional to the CD4 expression level and hence declines exponentially with time following the first infection." (PMID 17967052, 2007). "Animal models suggest that CD4+ T cells are the most important aspect of the protective response in primary infection." (PMID 17555578, 2007). "For this purpose, we used genetically deficient mouse strains that are described as highly susceptible to infection with T. cruzi such as MHC-II KO, CD4 KO, IL-12 KO and perforin KO." (PMID 17460760, 2007). "At two weeks after infection the CD4-independent-HIGH phenotype was observed in isolates from approximately half of the P and SP macaques, while at the same time-point this was the only phenotype present in LTNP macaques." (PMID 17645788, 2007). "CD4+ T cells producing cytokines were present in all infected mice at both time points during infection." (PMID 17555592, 2007).
infection (continued). "Infected CD4+ T cells harboring unintegrated HIV-1 DNA, which constitute a second form of latency named preintegration latency, are observed immediately after direct infection of resting CD4+ T cells." (PMID 17727722, 2007). "In a recent study, Dixit and Perelson developed a model that explicitly accounts for CD4 down-modulation and presents a rigorous description of the orchestration of multiple infections of cells by free virions." (PMID 17967052, 2007). "As early as two-weeks after infection four out of nine macaques with progressive disease harbored viruses that had changed to CD4-independent-LOW." (PMID 17645788, 2007). "Further, to address possible differences between the rates of first, second, and third infections, due, for instance, to CD4 down-modulation, Fraser postulates the use of different values of the rate constants, k, for successive infections." (PMID 17967052, 2007). "The effect of long-term infection with nef-deleted virus on CD4+ T cells was studied in detail for six SBBC members." (PMID 17888184, 2007). "A recent study with WNV illustrated the important role that CD4+ T cells play in controlling infection." (PMID 18000543, 2007). "At 3days post-infection, CD4/CD8 DP cells were observed in the lungs of both WT and Cd59a–/– B6 mice but significantly higher percentages were observed in Cd59a–/– mice." (PMID 17429844, 2007). "Next, purified quiescent CD4+ T cells were infected with the NL4.3 strain of HIV-1 at a multiplicity of infection (moi) of 1 and the subcellular localization of incoming sub-viral complexes was studied by immunofluorescence and confocal microscopy." (PMID 17845727, 2007). "Expansion occurs rapidly following infection, although, due to parallel expansion of CD25+Foxp3– cells in infection, there is in fact a small diminution in the proportion of CD4+CD25+ cells which express Foxp3." (PMID 17563918, 2007). "In accord with previous reports, it was confirmed that SHIVKu1 infection was at PID 14 associated with greater plasma viral loads and more profound loss of peripheral CD4+ T cells than that caused by SHIVSF162P4." (PMID 17684570, 2007). "In various infection models it has been documented that CD4+ T cell help is important for CD8+ T cell function and especially CD8+ T cell memory." (PMID 18000535, 2007). "Although HIV-1 efficiently entered both CD4+ T cells and LC, our findings indicated that the path of entry and fate of infection differed in the two cell populations." (PMID 17306567, 2007). "Similar results were observed at day8 post-infection and by day12, numbers of CD4+ T cells in lungs were similar for both groups of mice." (PMID 17429844, 2007). "Macrophages are also a significant viral reservoir in vivo, and are a significant source of sustained high level viremia at late stages of infection when virtually all CD4+ T-cells are depleted." (PMID 19088897, 2007). "Syncytia are formed when Env expressed on an infected cell late in infection interacts with CD4 of a neighboring cell, triggering the fusion peptide of TM to fuse the two membranes." (PMID 17945027, 2007). "Thirty days after infection we verified a significant CD4+ cells influx into lungs in all immunized, infected mice when compared with non-immunized infected mice and non-infected mice." (PMID 17714584, 2007). "A standard criterion for LTNP status is to have had a documented infection for ten years or more, stable CD4-positive T cell counts above 500 cells/ml, and plasma viral load below 10,000 RNA copies/ml." (PMID 17651505, 2007). "When each T cell subset isolated from an HIV-uninfected individual was challenged with R5.HIV, CD4 TCM and TEMRO cells were more susceptible to infection than TN cells, most likely reflecting high CCR5 surface expression levels on these memory T cells." (PMID 17465678, 2007). "The number of CD4+ T cells recovered from the lungs at day3 post-infection was strikingly higher in Cd59a–/– compared to WT mice." (PMID 17429844, 2007).
infection (continued). "Dendritic cells (DCs) have been implicated to play an important role in the transmission of HIV-1 and the establishment of infection through capturing virus and enhancing infection of CD4+ T-lymphocytes." (PMID 17263871, 2007). "We have also assumed that any PPC sequence found in resting CD4+ T cells is due to infection of that cell after initiation of HAART." (PMID 17784786, 2007). "By exposing isolated epithelial sheets to viable, fluorescence-tagged HIV-1, we can directly evaluate infection of intraepithelial Langerhans and CD4+ T cells." (PMID 17306567, 2007). "Most severely affected are the white blood cells known as T lymphocytes, particularly the CD4+ T cells that recognize infection and enable other cells of the immune system to respond." (PMID 17388662, 2007). "Control macaques showed a sharpincrease in the frequency of dying T and B cells within 1 week after infection;these values increased to peak levels of around 25% for CD4+ T cells, 30% forCD8+ T cell, and 40% for CD20+ B cells." (PMID 18317535, 2007). "To examine the mechanism of noncytolytic CD8+ T cell mediated suppression during the time of viral gene expression, we utilized a single cycle infection assay in primary CD4+ lymphocytes." (PMID 19440453, 2007). "Infection occurs after sequential interactions of gp120 with cellular CD4 and a coreceptor, usually CCR5 or CXCR4." (PMID 16817962, 2006). "A high level of activation of mucosal lymphocytes soon after infection was found to predict poor restoration of mucosal CD4 cells over time." (PMID 17147468, 2006). "The remaining macaque (P804) became infected with SIVmac055, but was able to control the infection and CD4+ T cells remained stable in this animal for over a year." (PMID 17184540, 2006). "The frequency of recombination catalyzed by Taq was < 0.005%/Kbp, or at least 100-fold less than that generated in dual infections of U87.CD4.CXCR4 cells." (PMID 17164002, 2006). "Just as DC-SIGN-expressing DCs capture and transport virus to the lymph node and propagate CD4 T cell infection in trans, so can syndecan-expressing macrophages." (PMID 16817962, 2006). "Although the kinetics of CD4 T cell loss differ, both the SCID-hu and hu-PBL-SCID mouse models support infection with either of the R5 and X4 HIV-1 viral strains." (PMID 17078891, 2006). "Our initial description of eight patients studied cross sectionally 6 mo to 5 y after the initiation of therapy during acute and early infection suggested that despite therapy, CD4+ T cell depletion persisted in the GI mucosa." (PMID 17147468, 2006). "Possible explanations include poor compliance, failure to reduce the viral load and raise the CD4+ lymphocyte count or dissociation between colonization and infection." (PMID 16423306, 2006). "Subsequently an HIV-1 inhibition assay was carried out to determine the anti-HIV-1 activity of the crude saliva and purified salivary mucins by incubating them with subtype D HIV-1 prior to infection of the CD4+ CEM SS cells." (PMID 17125499, 2006). "In the controls, where the virus was incubated with the media only, prior to addition to the CD4+ CEM SS cells at all time points (30 min, 1 h and 3 h), 100% of HIV-1 replication or infection of the CD4+ CEM SS cells was detected." (PMID 17125499, 2006). "The most potent inhibitor is Rgp41A, which inhibits the infection of HeLa-CD4 cells by HIV-1 LAI and ADA Env pseudotyped viruses with IC50 values of 56 and 156 nM, respectively." (PMID 16515685, 2006). "Infection experiments with pseudotyped or wild-type HIV-1 viruses on HeLa-CD4 or HeLa-CD4-CCR5 cells revealed that both Rgp41A and Rgp41B have the capacity to interfere with HIV-1 entry into target cells." (PMID 16515685, 2006). "The AIDS virus (HIV) is most active against the white blood cells called T lymphocytes, particularly the CD4 T lymphocytes, which recognize infection and activate other cells of the immune system to fight it." (PMID 17147468, 2006).